ENSG00000252188
Synonyms: LOC124900246
Gene: Small nucleolar RNA gene on chromosome 7 (138,625,060 to 138,625,179, reverse strand). Ensembl gene ENSG00000252188.
Gene Ontology:
Biological process: RNA processing
Cellular component: nucleolus
Homologues: Paralogues in human: SNORA40 (72% identical), SNORA40B (72% identical), SNORA40C (68% identical).